PGK1 (phosphoglycerate kinase 1)
Diseases named in the same sentence as PGK1 in open-access papers (continued):
Sharing a sentence is not in itself a finding about the gene and the disease.
cancer (continued). "To understand which cancers of PGK1 will seriously affect the prognosis of patients, so we have comprehensively screened the clinicopathological factors of PGK1 on patient survival rate." (PMID 34091600, 2021). "GBM tumors displayed distinct Warburg-like genetic features, with increased HK2, PGAM1, ALDOC, and PGK1 expression that facilitates lactate production and confers resistance to hypoxic stress in cancer cells." (PMID 35004842, 2021). "PGK1, the foremost regulator, was a comprehensively profiled pan‐cancer, and a PGK1‐based interactive network was established." (PMID 34668665, 2021). "Transcription factor SPI1 promotes aerobic glycolysis via upregulating HK2 and PGK1 in cancer cells." (PMID 34841706, 2021). "PGK1 is overexpressed in various cancer types, including bladder, brain, breast, colorectal, head and neck, kidney, lung and ovarian cancers." (PMID 33804240, 2021). "The mRNA expressions of PGK1 are also remarkably correlated with the cancer stage, and patients with advanced cancer stages tended to express higher mRNA expression of PGK1." (PMID 34291087, 2021). "In the current study, we demonstrate that as a transcriptional activator, SPI1 enriches on promoter regions of glycolytic enzymes HK2 and PGK1 and facilitates their expression in cancer cells." (PMID 34841706, 2021). "Previously, it has been reported that upregulation of PGK1 expression is observed in several types of cancer." (PMID 33747900, 2021). "As an essential enzyme in the glycolytic pathway, it is proved that PGK1 is directly regulated by HIF-1α in many cancer types." (PMID 34291087, 2021). "Herein, we conducted a pan-cancer analysis of the expression pattern and immunological features of PGK1." (PMID 34790279, 2021). "PGK1 is upregulated in numerous types of tumors, which is correlated with malignant biological behaviors of cancer cells." (PMID 34277429, 2021). "Taken together, the results of this study indicate that, we have identified a key metabolic gene, PGK1, which is critical for supporting cancer diagnosis and therapy." (PMID 34091600, 2021). "PGK1 is overexpressed in many cancers, and its role in promoting aerobic glycolysis in cancer is associated with poor clinical prognosis." (PMID 34221965, 2021). "PGK1, the central enzyme in the glycolysis pathway, controls the production of ATP during aerobic glycolysis and is upregulated in many types of human cancers." (PMID 34337858, 2021). "For instance, PGK1, a major enzyme regulating glycolysis, which produces ATP in cancer cells, also promotes cancer progression." (PMID 33833986, 2021). "In aerobic glycolysis, another of the glycolytic enzymes that are altered in cancer cells to promote and maintain the Warburg effect is the PGK1 enzyme, which has been observed to be overexpressed in breast, colon, and gastric cancer." (PMID 33809480, 2021). "After determining the crucial molecular relationships of PGK1, we explored this oncogene in a pan‐cancer analysis." (PMID 34668665, 2021). "Unlike previous investigations, we demonstrated that this novel function of PGK1 in cancer was not limited to chemotherapy/radiotherapy or to triggering autophagy in tumorigenesis." (PMID 34091600, 2021). "Increasing evidence suggests the prominent upregulation of PGK1 as an oncogene in various cancer types." (PMID 34790279, 2021). "How PGK1 interacts with these pathways to control glucose metabolism during cancer progression is worth exploring." (PMID 34091600, 2021). "Our findings identified a novel regulatory mechanism of GSK3β stabilization with PGK1 as a co-chaperone of Hsp90, and emphasized the potential of selecting Hsp90 inhibitors with GSK3β stabilization for more effective cancer treatments." (PMID 34403222, 2021). "The importance of PGK-1 in cancer development resides on its involvement in drug-resistance and its dual action depending on the cellular environment." (PMID 33536086, 2021).
cancer (continued). "The enzyme PGK1 also participates in many biological activities, such as angiogenesis, autophagy and DNA repair, hindering the comprehension of its role during cancer development." (PMID 33804240, 2021). "Following the TNMplot and UALCAN database data showed that the PGK1 transcriptional level was remarkably correlated with metastasis and cancer stages." (PMID 34291087, 2021). "Interest in its mechanisms is intensified by the fact that PGK1 is one of the only two enzymes that is involved in ATP production during aerobic glycolysis in cancer cells." (PMID 33804240, 2021). "Our pan-cancer analysis uncovered that PGK1 upregulation contributed to undesirable clinical outcomes for most of cancer types." (PMID 34790279, 2021). "Expression pattern and prognostic significance of PGK1 were comprehensively assessed across pan-cancer based on RNA-seq profiles from the TCGA project." (PMID 34790279, 2021). "PGK1 plays crucial roles in oncogenesis and progression of human cancers and contributes to poor prognosis." (PMID 34841706, 2021). "A decrease in two proteins was significant in this cell line following the expression in ESRP1 including phosphoglycerate kinase 1 (PGK1) a prognostic biomarker for cancer." (PMID 31963158, 2020). "High PGK1 expression was shown in various human cancers and correlated with poor prognosis of cancer patients." (PMID 33344462, 2020). "A recent comprehensive analysis of pan-cancer metabolic transformation also indicated that PGK1 was the most frequently upregulated gene in glycolytic pathway and had 100% frequency of upregulation in different types of cancer." (PMID 32070368, 2020). "Despite all this, there is an urgent requirement for clinical application to establish a selective targeted delivery system to inhibit PGK1 activity in cancer cells precisely." (PMID 32070368, 2020). "We observed that in the remaining samples, 23 pairs exhibited relatively higher level of PGK1 glycosylation in cancer tissues." (PMID 31911580, 2020). "In this study, we discovered for the first time that miR-16-1-3p is another PGK1 inhibitor, and can modulate cancer cell growth and metatstasis by a variety of biological function tests." (PMID 33344462, 2020). "Post-translational modifications of phosphoglycerate kinase 1 (PGK1), a glycoytic enzyme, contribute to cancer progression." (PMID 31911580, 2020). "Future studies are encouraged to demonstrate a novel mechanism of miR-6869-5p-inhibited tumorigenesis by regulating cancer cell metabolism and targeting PGK1 or other key enzymes." (PMID 32565733, 2020). "PGK1 is a glycolytic enzyme that participates in carcinogenesis, which can be produced by cancer cells and participates in regulating angiogenesis by decreasing disulfide bonds in serine protease and plasmin." (PMID 32565733, 2020). "PGK1 expression is upregulated in many types of human cancer, but the detail mechanisms by which PGK1 contributes to cancer development are not well understood." (PMID 31911580, 2020). "The results showed that P4HA1 was correlated with PGK1 (r = 0.16~0.81) in 25 cancer types and correlated with LDHA (r = 0.13~0.79) in 24 cancer types (p < 0.05)." (PMID 32635458, 2020). "HSPA8 was associated with most of glycolytic genes like PGK1 (r = 0.21~0.79) and PGAM1(r = 0.17~0.80) across all cancer types (p < 0.05)." (PMID 32635458, 2020). "The overexpression of PGK1 has been found to not only promote the proliferation of cancer cells, but also relate to multidrug resistance phenotype." (PMID 32850805, 2020). "Glycolytic enzymes, in particular pyruvate kinase (PK) and PGK 1 (PGK1) play central roles in cancer cell proliferation." (PMID 31198853, 2019). "Here, we investigated the relationship between the progression and prognosis of multiple cancer types and PGK1 expression and its function in the mitochondrial metabolism regulation." (PMID 31578148, 2019).
cancer (continued). "Expression of HPRT1, Jag2, AURKA, and PGK1 were elevated when compared to normal samples, and HPRT1 and PGK1 showed a stepwise elevation in expression that was significantly related to cancer grade." (PMID 30679932, 2019). "The up-regulation of PGK1 involved in the Warburg effect has been detected in several types of human cancer." (PMID 31578148, 2019). "Kaplan–Meier analysis showed that higher levels of both PGK1 pS203 and PDHK1 pT338 were associated with shorter OS in patients with these five cancer types (all P < 0.05)." (PMID 31578148, 2019). "We further investigated the downstream molecular mechanism by which PGK1 regulates cancer cell proliferation." (PMID 30925862, 2019). "The PGK1 mRNA level was significantly elevated with hypomethylation in promotor regions and associated with advanced TNM stage in 15 and four cancer types, respectively." (PMID 31578148, 2019). "We next determined the methylation status of the PGK1 gene in 14 cancer types with significantly elevated PGK1 mRNA levels in the TCGA data." (PMID 31578148, 2019). "Phosphoglycerate kinase 1 (PGK1) is a glycolytic enzyme that has recently been shown to be related to the poor prognosis of various types of cancers." (PMID 30925862, 2019). "The analysis of the TCGA cancer genome database also revealed that the mRNA expression of gankyrin was clinically correlated to PGK1, an upstream protein kinase of AKT." (PMID 30420909, 2018). "The PGK1/G6PD-marked hypermetabolic CTCs (GM+CTCs) are promising biomarkers for the diagnosis of cancer metastasis." (PMID 29954422, 2018). "PGK1 is an enzyme responsible for the first ATP-generating step in the glycolysis pathway and is highly expressed in many types of cancer." (PMID 30367676, 2018). "Our study reveals that most of the PGK1 nsSNVs found in cancer tissues display a decreased catalytic efficiency together with a destabilization of the native state." (PMID 29995887, 2018). "In conclusion, the present paper discloses the structure and functional features of nsSNVs of PGK1 found in cancer cells: R38M, R65W, G166D, M189I, A199V, V216F and F241S." (PMID 29995887, 2018). "And it can be proposed that PCAF‐induced K323 acetylation of PGK1 enhances its activity and promotes cancer cell proliferation and tumorigenesis." (PMID 30216660, 2018). "In this study we selected seven PGK1 nsSNVs found in cancer tissues and annotated in the COSMIC database." (PMID 29995887, 2018). "Many studies have shown that PGK1 acts as a protein kinase in coordinating glycolysis and autophagy, which is instrumental in cancer metabolism and tumorigenesis." (PMID 29416645, 2018). "PGK1 is a central enzyme in the cancer cells metabolism since they utilize preferentially glycolysis to produce ATP." (PMID 29995887, 2018). "The results demonstrated that the GM+CTCs marked by PGK1 and G6PD were closely associated with the patients’ clinical stage, cancer metastasis and serum tPSA level, although they made up only a small part of the total CTCs." (PMID 29954422, 2018). "Many types of cancers, including those of the breast, the colon, the liver and others, have been shown to exhibit an increased expression of PGK1." (PMID 28686225, 2017). "In general, tumors develop region of hypoxia, therefore the PGK1 activity in the cancer cells is higher than in the normal cells." (PMID 28903403, 2017). "A recent article shows that acetylation at the K323 site of PGK1, as an important regulatory mechanism, promotes its enzymatic activity and cancer cell metabolism." (PMID 28749413, 2017). "As before, we compared the expression of PKC coding genes in normal and cancer tissue with the data normalised to either PGK1 alone or PGK1, GUSB and PP1A together." (PMID 26962435, 2016). "Both ERRα and ERRβ stimulate the expression of HIF-1 target genes such as erythropoietin, the key angiogenic factor VEGF, and the glycolytic enzyme PGK-1 in human cancer cell lines." (PMID 23050013, 2012).
cancer (continued). "To evaluate the pan-cancer relevance of this mechanism, we assessed whether PGK1-mediated phosphorylation of MORC2 at S711 promotes radioresistance beyond PDAC." (PMID 41213904, 2025). "Collectively, these data indicate that the PGK1/MORC2 axis not only drives radioresistance in PDAC but may exhibit broader relevance in other cancers." (PMID 41213904, 2025). "Furthermore, beyond its metabolic functions, PGK1 has been increasingly recognised for its non‐metabolic roles in various cellular processes, particularly in cancer progression." (PMID 40534132, 2025). "PGK1, which generates ATP during glycolysis, may facilitate ATP production through its upregulation, thus meeting the energy demands of cancer cells." (PMID 40692714, 2025). "Interestingly, during our exploration of downstream of ALDOC, its co-expression feather with PGK1, another key enzyme in glycolysis as well as in cancer development, brings our eyes back to the relevant field of glycolysis." (PMID 40518543, 2025). "Comparison of PGK1 positive expression in cancer tissues and adjacent tissues [n (%)]." (PMID 40771921, 2025). "Therefore, PGK1 has emerged as a promising target for therapeutic intervention in cancer, with ongoing research focused on developing strategies to inhibit its function or reduce its expression." (PMID 39594816, 2024). "In addition, there is growing interest in targeting PGK1 due to its role in glycolysis, cancer metabolism, and other diseases." (PMID 39712033, 2024). "PGK1 expression is upregulated in many types of human cancer." (PMID 39695074, 2024). "Importantly, the depletion of PGK1 markedly reduces cancer glycolysis, cell proliferation, and tumorigenesis of HCC in mouse xenograft models." (PMID 38997696, 2024). "PGK1 has been reported to be upregulated in various cancer types, such as lung and colon cancers." (PMID 39594816, 2024). "Thus, larger population-based studies are still needed to further confirm the utilization of PGK1 as a biomarker in cancer." (PMID 37723547, 2023). "Many previous studies have shown that PGK1 has a function in malignant tumors." (PMID 36860848, 2023). "Recently, an increasing number of studies have proven that PGK1 plays an important role in cancer." (PMID 37723547, 2023). "The acetylation of Pgk1 (K323) reportedly promotes its enzyme activity and cancer cell metabolism." (PMID 37278715, 2023). "In addition, SIRT7 is reported to reduce the activity of phosphoglycerate kinase 1 (PGK1) through its deacetylation in cancer cells." (PMID 38201252, 2023). "In conclusion, phosphorylation of PGK1 at various sites may be an attractive approach for cancer treatment." (PMID 37723547, 2023). "In conclusion, promoting the degradation of PGK1 by increasing its ubiquitination may be an effective strategy for PGK1-targeted cancer therapies." (PMID 37723547, 2023). "A possible mechanism to overcome drug resistance induced by sorafenib in cancer cells with high PGK1 expression might be the inhibition of the kinase with small inhibitors." (PMID 36675137, 2023). "PGK1 is highly expressed in a variety of cancer cells (Li, Zheng & Lu, 2016)." (PMID 36684675, 2023). "PGK1 is overexpressed in most cancers and suggests a poor prognosis in some cancer types." (PMID 36807568, 2023). "Indeed, PGK1 overexpression or amplification is often observed in many different types of human cancers, which, importantly, is correlated with poor survival of cancer patients." (PMID 37723547, 2023). "However, there are several challenges in the use of PGK1 as a clinical biomarker for the diagnosis, prognosis and treatment of various types of cancers." (PMID 37723547, 2023). "Specifically, NFAT5 promotes cancer progression via transcription of PGK1." (PMID 37208732, 2023). "This review presents an overview of the different roles played by PGK1 during tumorigenesis, which will help in the design of experimental studies involving PGK1 and enhance the potential for the use of PGK1 as a therapeutic target in cancer." (PMID 37723547, 2023).
cancer (continued). "High extracellular PGK1 levels suppress cancer malignancy by inhibiting angiogenesis." (PMID 37723547, 2023). "Similarly to phosphoglycerate kinase 1, annexin A1 can take part in a wide variety of cancer processes, including carcinogenesis, cell proliferation, invasion, apoptosis, and metastasis." (PMID 37834061, 2023). "Several studies have demonstrated PGK1 is directly regulated by HIF-1α in many cancers." (PMID 35121728, 2022). "This study would provide novel insights for understanding the role of PRAS40 and PGK1 in autophagy-mediated cell death, which could offer new clues to target cancers." (PMID 35058442, 2022). "And the high level of PGK1 was indicative of undesirable overall survival for various cancers." (PMID 36388159, 2022). "The mRNA expression of PGK1 was analyzed at pan-cancer and LUAD levels, respectively, and the results showed that the mRNA expression of PGK1 of “Not profiled” was higher than that of “No mutation” at the pan-cancer level." (PMID 36358653, 2022). "Indeed, the enzyme activity of PKM2 in cancer cells is very low, so PGK1 is probably more important than other glycolysis related enzymes for tumorigenesis." (PMID 35121728, 2022). "Since we focused on the function of PGK1 in cancer cell activity, we chose to overexpress PGK1 in 786-O and ACHN cells with relatively low expression of PGK1, and knock down PGK1 in OS-RC-2 cells that had a relatively high expression of PGK1 to perform follow-up analysis." (PMID 35121728, 2022). "However, the high extracellular expression of PGK1 inhibits malignant tumors by inhibiting angiogenesis." (PMID 36358653, 2022). "Thus, we proposed that PGK1 promoted the cancer phenotype through protein–protein interaction or post-translational modification." (PMID 34091600, 2021). "There was increase and decrease in SPI1 enrichment, promoter‐luciferase reporter activity, as well as levels of HK2 and PGK1 in cancer cells stably over‐expressing or silencing SPIB, which was eliminated by silencing or ectopic expression of SPI1, respectively." (PMID 34841706, 2021). "In addition, forced or impaired SPI1 expression respectively enhanced or reduced the levels of HK2 and PGK1 in cancer cells." (PMID 34841706, 2021). "Furthermore, we found that PGK1 displayed correlations to hallmarks of cancer including glycolysis, mTORC1 signaling, hypoxia, Hedgehog signaling, Wnt β-catenin signaling, myogenesis, and KRAS signaling." (PMID 34790279, 2021). "In addition to the metabolic functions of PGK-1 in cancer cells, this enzyme induces and increases the angiostatin formation and leads to the restriction of angiogenesis in tumours." (PMID 33536086, 2021). "PGK1 is a crucial catalytic enzyme in glycolysis and is overexpressed in many cancers." (PMID 34221965, 2021). "The role of Pgk1 in the coordination of glycolysis and tricarboxylic acid cycle by increasing lactate production and suppressing mitochondrial pyruvate utilisation is well established in cancer cells." (PMID 33568709, 2021). "Furthermore, high PGK1 levels exhibited prominent correlations to immune checkpoints and high response to immunotherapy across pan-cancer." (PMID 34790279, 2021). "Moreover, we identified that the PGK1 protein translocated from the cytoplasm to the nucleus in malignant cancer cells and advanced patients." (PMID 34091600, 2021). "PGK1 has gradually become a novel target in clinical research for various cancers." (PMID 34668665, 2021). "We also proposed that PGK1 may have additional roles in tumorigenesis through interaction with molecules to regulate several phenotypes or the permanent environment for cancer cells, both in metabolic abundancy and deprivation statuses." (PMID 34091600, 2021). "High PGK1 expression was indicative of undesirable overall survival, progression-free interval, disease-specific survival, and disease-free interval for various cancers." (PMID 34790279, 2021). "We also comprehensively analyzed the role of PGK1 in several cancer types." (PMID 34091600, 2021).